KEAP1 (kelch like ECH associated protein 1)
Diseases named in the same sentence as KEAP1 in open-access papers (continued):
Sharing a sentence is not in itself a finding about the gene and the disease.
non-small cell lung carcinoma (continued). "However, they investigated head and neck, and non-small-cell lung cancer cells, respectively, and mainly focused on the modulation of Keap1 and Nrf2." (PMID 37760834, 2023). "In particular, KEAP1 and NRF2 mutations are encountered in 20–30% of non-small cell lung cancers." (PMID 32112372, 2020). "In melanoma and non-small cell lung carcinoma cell lines with or without KEAP1 mutations, NQO1 expression and 17-AAG sensitivity are inversely correlated." (PMID 27045471, 2016). "However, Keap1 has also been shown to be dysfunctional in non-small cell lung carcinomas that have elevated levels of NRF2." (PMID 26247201, 2015). "Our sequencing results confirmed the previously identified KEAP1 mutations in the A549 and NCI-H460 non-small cell lung cancer cell lines and identified a novel mutation (Q193H) in the NCI-H23 cell line, which is also derived from non-small cell lung cancer." (PMID 26301506, 2015). "In addition, among non-small cell lung cancer patients, KEAP1 and STK11 mutated patients are not sensitive to immunotherapy and have shorter disease-free and overall survival." (PMID 37973895, 2023). "In addition, we also assessed the activity of NSLC01, an immortalized normal pancreatic ductal epithelial cell line (hTERT-HPNE) and non-small cell lung cancer cells with or without constitutive NRF2 activation due to different mutation statuses of KEAP1 gene." (PMID 34247201, 2021). "Several studies reported that either loss of NRF2–KEAP1 interaction or point mutations in the KEAP1 or NRF2 gene are often observed in human cancers, such as renal cell carcinoma, chronic lymphocytic leukemia, esophageal squamous cell carcinoma, HCC, non-small cell lung cancer, and others." (PMID 28553614, 2017). "For instance, the defects of KEAP1 lose the ability to target EMSY for ubiquitin-mediated degradation and contribute to the development of non-small cell lung cancer." (PMID 40002690, 2025). "This review describes the mechanisms of targeted-drug resistance and newly identified non-small cell lung cancer targets (e.g., KRAS G12C, NGRs, DDRs, CLIP1-LTK, PELP1, STK11/LKB1, NFE2L2/KEAP1, RICTOR, PTEN, RASGRF1, LINE-1, and SphK1)." (PMID 36909198, 2023). "Non-small cell lung cancer (NSCLC) cells often possess a hypermethylated Keap1 promoter, which decreases Keap1 mRNA and protein expression levels, thus impairing the Nrf2-Keap1 pathway and thereby leading to chemo- or radio-resistance." (PMID 27029077, 2016). "By preventing methylation of the Keap1 gene promoter area, genistein selectively reduced radio sensitizing effects in non-small cell lung cancer (NSCLC) A549 cells; hypermethylation of the Keap1 promoter resulted in chemo/radio resistance mediated by the Nrf2-Keap1 pathway." (PMID 36571647, 2022). "VUSs predicted to be pathogenic—particularly in genes like KEAP1 and SMARCA4—are consistently associated with poorer overall survival in two nonoverlapping non-small cell lung cancer cohorts, and tend to be mutually exclusive with other known oncogenic alterations within the same pathways." (PMID 41006257, 2025). "TRIM15 could regulate the Wnt/β-catenin signaling pathway and Keap1-Nrf2 pathway and mediate the ubiquitination of APOA1 and ERK to promote the development and progression of cancers such as non-small cell lung cancer, esophageal squamous cell carcinoma, and pancreatic cancer." (PMID 36189312, 2022). "Genistein mediated selective radiosensitizing effects in non-small cell lung cancer (NSCLC) A549 cells by inhibiting the methylation of the Keap1 gene promoter region; hypermethylation of the Keap1 promoter results in chemo/radioresistance mediated by the Nrf2-Keap1 pathway." (PMID 34025826, 2021).
non-small cell lung carcinoma (continued). "Also, the analysis of non-small cell lung carcinomas in the TCGA data bank showed that, although there is a strong correlation between NRF2 and KEAP1 gene expression, there is a subset of patients with median expression of NRF2 and very low expression of KEAP1." (PMID 31776385, 2019). "In non-small-cell lung cancer cells, diosmetin does not alter mRNA transcription of NRF2 but interferes with the stability of Nrf2 through Keap1-mediated proteasomal degradation." (PMID 35242278, 2022).
diabetes (95 papers, 2013 to 2026). "Diabetes induction caused a considerable reduction in Nrf-2 expression (P<0.05) and an increase in Keap-1 expression (P<0.05) in the diabetic group, as reported in a previous study." (PMID 38234664, 2024). "Given that studies in this field have been performed on animal models and no results have been obtained in humans, more studies are needed, especially related to Keap1 variants and the risk of development of diabetes and its complications." (PMID 34861061, 2022). "Elevating CXCR7 expression preserved the functional activity of diabetic EPCs and protected against diabetes-associated oxidative stress damage by activating the Keap-1/Nrf2 axis in vivo and in vitro." (PMID 33941256, 2021). "It has also been reported to interact with Kelch-like ECH-associated protein 1 (Keap1) to protect organs/tissues of diabetics against diabetes-induced organopathy." (PMID 34956587, 2021). "The protein–protein interaction (PPI) of Keap1-Nrf2 is implicated in several neurodegenerative diseases like cancer, diabetes, and cardiomyopathy." (PMID 31726716, 2019). "This study showed that BAI alleviated diabetes-associated cardiac dysfunction and cardiomyocyte injuries in vivo and in vitro via Keap1/Nrf2/AMPK-mediated antioxidation and lipid-lowering effects." (PMID 31354905, 2019). "Diabetes increases retinal Nrf2 binding with Kelch-like ECH-associated protein 1 and decreases its DNA-binding ability, leading to decreased antioxidant gene transcription." (PMID 30373222, 2018). "Concordantly, activation of the Nrf2 pathway by disrupting the Keap1/Nrf2 complex and enhancing the p47phox/Nrf2 complex might be a prospective approach for the prevention and treatment of diabetes-associated complications, such as atherosclerosis." (PMID 36163178, 2022). "In addition, some proteins, such as inhibitor of nuclear factor kappa B kinase subunit beta (IKKβ), protein kinase C (PKC), and Kelch-like ECH-associated protein 1 (Keap1) that are damaged by redox modifications are responsible for the development of diabetes." (PMID 36014561, 2022). "It has been reported that exogenous H2S improves diabetes-accelerated atherosclerosis through inhibiting oxidative stress via Kelch-like ECH-associated protein 1(Keap1) sulfhydrylation of Cys151 to activate nuclear factor erythroid-2 related factor 2(Nrf2) signaling." (PMID 34201520, 2021). "Once in the status of diabetes, disrupted internal environment produce excessive ROS and the consequently launched autophagy, which prompts p62 to bind with Keap1 and subsequently inactivates Nrf2, causing a series of consequent complications, such as cardiac dysfunction." (PMID 31856386, 2020). "Interestingly, recent work in tissue regeneration models has demonstrated that hyperglycemia in diabetes is associated with Keap1 dysfunction, which prevents nuclear localization of Nrf2 and thus is an appropriate stress response." (PMID 28913364, 2017). "The most prominent member is the BTB–BACK (BTB and C-terminal Kelch)–Kelch protein KEAP1 (Kelch-like ECH-associated protein 1), a master regulator of the oxidative stress response and a potential drug target for common conditions such as diabetes, Alzheimer's disease and Parkinson's disease." (PMID 24450635, 2014). "Variants of Keap1 could affect susceptibility to diabetes and its complications." (PMID 34861061, 2022). "In addition, the roles of master antioxidant pathway nuclear factor erythroid 2-related factor 2 (Nrf2)/Kelch-like ECH-associated protein 1 (Keap1)/antioxidant response elements (ARE) are being deciphered to explain various molecular pathways involved in diabetes." (PMID 33299532, 2020). "The Kelch-like erythroid-associated protein 1 (Keap1)–NF-E2-related factor 2 (Nrf2) signaling pathway is the subject of several clinical trials evaluating the effects of Nrf2 activation on the prevention of cancer and diabetes and the treatment of chronic kidney disease and multiple sclerosis." (PMID 29367259, 2018).
diabetes (continued). "Some neuroprotective mechanisms can be attributed to the Keap1 and Nrf2, two key nuclear transcription factors involved in systemic and local antioxidant defense, including diabetes, DR, and likewise VRD." (PMID 40722945, 2025). "Emodin is a rhubarb-derived anthraquinone and was shown to reverse diabetes-induced Nrf2 suppression by modifying Keap1 cysteine levels, thereby enhancing cellular antioxidant defenses." (PMID 40276370, 2025). "While there is limited information about liraglutide’s impact on Keap1, these findings suggest liraglutide’s potential as an effective Nrf2-related antioxidative treatment for diabetes-induced atherosclerosis." (PMID 38255895, 2024). "Results demonstrated the anti-oxidant activity of PHE in a dose-dependent manner by increasing Nrf-2 nuclear translocation and decreasing Keap-1 mRNA expression in pancreatic tissues of rats with alloxan-induced diabetes." (PMID 38234664, 2024). "Bone marrow–derived multipotent stromal cells (BMSCs) have a low expression of cytoprotective NRF2/Keap1 in diabetes." (PMID 38158644, 2024). "It will also highlight how treatments for diabetes that specifically target the Nrf2/Keap1 pathway have similar benefits on each comorbidity." (PMID 38255895, 2024). "The findings from our in vivo and in vitro studies are in line with previous research, indicating that the Keap1-Nrf2 system plays a crucial role in preventing the onset of diabetes." (PMID 38671848, 2024). "With the significance of oxidative stress in diabetes confirmed, the protective properties of the Nrf2/Keap1 activation become an important strategy for the resolution of hyperglycemia-induced oxidative stress and organ damage." (PMID 38255895, 2024). "In this manner, CoQ10 serves to increase antioxidant activities through the induction of the Nrf2/Keap1/ARE pathway, thereby potentially alleviating the impact of diabetes and its associated cardiovascular complications." (PMID 38524871, 2024). "As a potent antioxidant target that can be a key to the treatment of diabetes and various diabetic comorbidities, the Nrf2/Keap1 signaling pathway remains worthy of further investigation." (PMID 38255895, 2024). "In a study with alloxan induced type 1 diabetes mellitus in mouse-derived pancreatic islet β-cell line, the isoflavonoid formononetin, a component of Astragalus gallinaceus Bunge, activates the KEAP1/Nrf2 signaling pathway, decreasing oxidative stress." (PMID 39334784, 2024). "Keap1/Nrf2 signaling plays a key role in diverse diseases, including diabetes, cancer, neurodegenerative diseases, airway diseases, inflammatory diseases, cardiovascular diseases, and aging." (PMID 37920252, 2023). "The association between the interaction of KEAP1 and NFE2L2 has been implicated in the pathogenesis of various chronic conditions, such as diabetes, cancer, and neurodegenerative illnesses." (PMID 37794491, 2023). "H2S increased S-sulfhydration of kelch like ech associated protein 1 (KEAP1) and nuclear erythroid 2-related factor 2 (NRF2) nuclear translocation to attenuate diabetes-accelerated atherosclerosis." (PMID 37244925, 2023). "Here, Keap1 inhibitors are potential drug candidates for oxidative-stress-induced diseases including cancer, diabetes, and neurodegenerative diseases." (PMID 37299017, 2023). "For example, global low phenotypic knockout of the endogenous inhibitor of NRF2, Kelch-like ECH-associated protein 1 (Keap1), activates the NRF2 gene and thus inhibits the development of diabetes in db/db mice." (PMID 37468902, 2023). "In diabetes, the increased ROS production leads to autophagy activation, which prompts p62 to bind with Keap1 and subsequently inactivates Nrf2." (PMID 37688651, 2023). "Both EKE and GEKE can improve diabetes and kidney disease by improving hyperglycemia, oxidative stress, and kidney physiological indicators and regulating the Keap1/Nrf2/HO-1 and AMPK/mTOR pathways." (PMID 36832842, 2023).
diabetes (continued). "Among these signaling pathways, AMPK/mTOR and Nrf2/Keap1 are the principal ones that Sestrin2 is suggested to be involved in the pathogenesis of diabetes and diabetic complications." (PMID 37920252, 2023). "In a diabetes mellitus model, miR-223 regulated the Keap1/Nrf2 pathway to affect oxidative stress in a hepatocarcinoma cell line." (PMID 37710276, 2023). "Overexpression of Nrf2 (Keap1 knockdown) can act as a protective role in diabetes complications such as neuropathy." (PMID 34861061, 2022). "In a mouse model of diabetes, it has been demonstrated that KEAP1 knockout, by promoting NRF2 activation, improved insulin secretion and insulin resistance and resulted in the prevention of hyperglycemia." (PMID 35955599, 2022). "This study demonstrated that synergistic regulation of Keap1 and p47phox by Rb1 contributes to Nrf2 activation in ECs, thus protecting against endothelial dysfunction and diabetes-accelerated atherosclerosis." (PMID 36163178, 2022). "For example, cell stress response mediator NRF2 is excessively degraded due to its increased binding to KEAP1 in diabetes." (PMID 35873915, 2022). "Genetic activation of Keap1/Nrf2 in diabetic animal models has been shown to alleviate insulin resistance and to prevent the onset of diabetes mellitus." (PMID 34947831, 2021). "In diabetes, Nrf2 expression and its binding with Keap1 are augmented in the retina as well as DNA binding activity of Nrf2 and GSH levels are reduced." (PMID 34946740, 2021). "Nrf-2/Keap-1 system controls the antioxidant redox signaling to repress the initiation of diabetes mellitus." (PMID 33819919, 2021). "The Keap1/Nrf2 pathway is a promising target for the management of metabolic syndrome and type 2 diabetes mellitus." (PMID 34947831, 2021). "The cytoprotective Nrf2/Keap1 pathway is a key player in the prevention of oxidative stress; therefore, its dis-regulation results in diabetes and its complications as a characteristic of insulin resistance (IR)." (PMID 34946740, 2021). "Activation of Keap1/Nrf2 signaling manifests advantageous effects in a several disease states including diabetes, atherosclerosis, malaria, liver injury, obesity, neurodegenerative diseases, and certain cancers." (PMID 32848508, 2020). "Activation of Nrf2 by its activator or inhibiting its repressor Keap1 alleviated ROS generation, decreased oxidative damage, and accelerated wound closure in diabetes." (PMID 32566084, 2020). "It is of note, however, that in these reports, Nrf2 repression during diabetes or chronic hyperglycemia often accompanies increase of Keap1 protein level." (PMID 32079324, 2020). "In summary, allicin improved plasma TAS and reversed the changes in Nrf2 and Keap1 expression, showing its renal antioxidant effects on diabetes." (PMID 33203103, 2020). "Nrf2 is inactivated in certain pathological conditions, such as diabetes, but Keap1 down-regulation or mtROS elimination rescues Nrf2 expression and improves the pathology." (PMID 32079324, 2020). "Here, we demonstrated that allicin is able to improve the TAS as well as Nrf2/Keap1 ratio in diabetes." (PMID 33203103, 2020). "As a key pathway for oxidative stress, the Keap1/Nrf2/ARE system plays an important role in the study of diabetes." (PMID 30781644, 2019). "Activation of Keap1/Nrf2 signaling exerts beneficial effects in numerous disease states including atherosclerosis, diabetes, liver injury, malaria, obesity, neurodegenerative diseases and certain cancers." (PMID 29396403, 2018). "While the mechanism or mechanisms of this dysfunction in diabetes have only begun to be elucidated, therapies targeting the Nrf2/Keap1/ARE pathway represent a promising avenue in current research." (PMID 28913364, 2017). "This seems to support the notion that aberrant overexpression of Keap1 and resulting Nrf2 repression is a possible mechanism of the redox homeostasis dysfunction and impaired wound healing in diabetes." (PMID 28913364, 2017).